SIAH2 (siah E3 ubiquitin protein ligase 2)
Diseases named in the same sentence as SIAH2 in open-access papers (continued):
Sharing a sentence is not in itself a finding about the gene and the disease.
prostate carcinoma (17 papers, 2010 to 2025). A carcinoma that arises from epithelial cells of the prostate gland. "Updated research has demonstrated that the RNA helicase DEAH-box (DHX) 15 stabilizes E3 ligase Siah2 and enhances Siah2 activity, thus ubiquitinates and degrades AR, whereas enhanced AR transcriptional activity contributes to prostate cancer progression." (PMID 35002522, 2022). "The AR-SIAH2 interaction has been most extensively studied in prostate cancer where it regulates hormone sensitivity of tumor cells in conjuction with NCoR1, another SIAH2 substrate that also interacts with REVERBα." (PMID 35789210, 2022). "SIAH2 participated in the regulation of EAF2 polyubiquitin in prostate cancer cells as E3 ligase of EAF2 polyubiquitination." (PMID 32296631, 2020). "SIAH2 was reported to increase in castration resistant prostate cancer and stimulate castration resistant activation of AR." (PMID 27058417, 2016). "Under normoxia, the ability of Siah2 to modulate cell proliferation in lung cancer cells has been detailed; a finding we have confirmed in prostate cancer cells." (PMID 21586138, 2011). "Silencing Siah2 or POSH in prostate cancer cells led to increased caspase activity and apoptosis in response to both TRAIL and Fas ligand." (PMID 21586138, 2011). "Protein Wnt-5a (Wnt5a) expression in the osteoblastic niche has been found to promote dormancy in a model of prostate cancer via the activation of the Wnt5a/tyrosine-protein kinase transmembrane receptor ROR2 (ROR2)/E3 ubiquitin-protein ligase SIAH2 (SIAH2) signalling axis." (PMID 36701089, 2023). "In addition, AKR1C3 binds and stabilizes the ubiquitin ligase Siah-2, inhibiting its degradation, thereby enhancing Siah-2-dependent down-regulation of the AR corepressor NCoR in prostate cancer cells." (PMID 35582223, 2020). "In addition, a recent study identified a role of Siah2 in the development and progression of castration‐resistant prostate cancer." (PMID 26832397, 2016). "However, the regulation of Siah2 in prostate cancer (PCa) is largely unknown." (PMID 33937036, 2021). "The observed apoptosis resistance provides one biological explanation for the induction of Siah2 and POSH reported in lung and prostate cancer, respectively." (PMID 21586138, 2011). "Noncanonical Wnt5a supports prostate cancer dormancy in the bone microenvironment via its cognate receptor Ror2 and induction of downstream Siah E3 Ubiquitin Protein Ligase 2 (SIAH2)." (PMID 37440925, 2023). "The ubiquitin ligase Seven-in absentia homolog 2 (SIAH2) is a RING-type ubiquitin ligase well-described as an oncoprotein that promotes metastasis of breast, melanoma and prostate cancer, likely via regulation of hypoxic responses that characterize tumorigenicity." (PMID 35313831, 2022). "Oncomine analysis revealed Siah2 to be significantly overexpressed in both B-cell acute lymphoblastic leukemia and squamous non-small-cell lung carcinoma, while POSH is one of the most frequently overexpressed genes in prostate cancer." (PMID 21586138, 2011). "Furthermore, defining the regulatory axis consisting of Siah2 and HIF-1α/FoxA2 cooperation suggests novel therapeutic modalities to treat these most aggressive forms of prostate cancer." (PMID 21037926, 2010). "The elevated expression of SIAH2 may not only increase the transcriptional activity of AR, but also potentially reduce EAF2 protein level and its potential tumor suppressive activity, further promoting malignant growth of prostate cancer." (PMID 27058417, 2016).
cholangiocarcinoma (10 papers, 2022 to 2025). A carcinoma that arises from the intrahepatic biliary tree (intrahepatic cholangiocarcinoma) or from the junction, or adjacent to the junction, of the right and left hepatic ducts (hilar cholangiocarcinoma). "In this study, we showed that METTL14, a component of the m6A methyltransferase complex, induced Siah2 expression in cholangiocarcinoma (CCA)." (PMID 35154166, 2022). "The ubiquitination of PD-L1 in cholangiocarcinoma (CCA) is diminished by METTL14 through YTHDF2-mediated inhibition of the RING E3 ubiquitin ligase Siah2, and the deprivation of Siah2 represses T-cell expansion and toxicity by maintaining tumour PD-L1 expression." (PMID 36859310, 2023). "In cholangiocarcinoma, METTL14 induced the expression of seven in absentia homolog 2(Siah2) in cholangiocarcinoma, which in turn promoted PD-L1 expression levels in cholangiocarcinoma." (PMID 39033180, 2024). "Similar to NSCLC, in cholangiocarcinoma (CCA), METTL14 binds Siah2 mRNA in the 3′-UTR region and triggers m6A modification, promoting its degradation in a YTHDF2-dependent manner." (PMID 36960074, 2023). "Similarly, in cholangiocarcinoma, METTL14 mediates m6A modification of Siah2 and promotes the degradation of Siah2 upon reading by YTHDF2, inhibiting the ubiquitination of PD-L1 mediated by Siah2, ultimately leading to an increase in PD-L1 expression levels." (PMID 39372415, 2024). "In cholangiocarcinoma (CCA), METTL14 increases m6A modifications in the 3′UTR region of Siah2 mRNA, leading to its degradation via a YTHDF2‐dependent mechanism." (PMID 39802639, 2025). "Similarly, METTL14 facilitates the degradation of Siah2 mRNA through m6A modification and YTHDF2-mediated decay in cholangiocarcinoma (CCA)." (PMID 40034695, 2025).
melanoma (10 papers, 2014 to 2024). A malignant, usually aggressive tumor composed of atypical, neoplastic melanocytes. "Another recent study has implicated SIAH2 in immune evasion of melanoma by promoting Treg proliferation via degradation of p27." (PMID 33842469, 2021). "The authors concluded that SIAH2 controls Treg-cell recruitment and its loss in the host sensitizes melanoma to anti-PD-1 treatment." (PMID 33800394, 2021). "Growth of anti-PD-1 therapy resistant melanoma is effectively inhibited in Siah2−/− mice subjected to PD-1 blockade, indicating synergy between PD-1 blockade and Siah2 loss." (PMID 31911617, 2020). "Overall, Siah2 regulation of Treg recruitment and cell cycle progression effectively controls melanoma development and Siah2 loss in the host sensitizes melanoma to anti-PD-1 therapy." (PMID 31911617, 2020). "Addition of TM also caused a notable increase in Siah2 mRNA levels in several other cell lines including HeLa, and the melanoma cell line LU1205 (>3-fold)." (PMID 24809345, 2014). "A significant positive correlation between expression of SIAH2 and the immune gene signature of tumors grown in our Siah2−/− mouse model signified the immune-responsive human melanoma tumors." (PMID 31911617, 2020). "Here, the authors show that Siah2 null immune cells have an increased inflammatory response to inoculated melanoma cells, along with a reduced number of infiltrating immunosuppressive regulatory T cells, resulting in inhibition of tumour growth." (PMID 31911617, 2020). "In Malme3MR cells (anti-cancer drug-resistant melanoma cells), SIAH2 can binds to HDAC3, resulting in degradation of HDAC3 by ubiquitination." (PMID 30583572, 2018). "Menadione has been identified as a specific inhibitor of the E3 ubiquitin ligase Siah-2 which is generally up-regulated in melanoma." (PMID 26213971, 2015). "Another study demonstrated that a dominant-negative SIAH2 ring finger mutant increased the amount of SPRY2 in SW1 melanoma cells and decreased tumorigenesis and metastasis, which is consistent with the role of SIAH2 in controlling the concentration of SPRY proteins." (PMID 39456824, 2024). "A positive correlation between SIAH2 and FOXP3 (Tregs marker) expression suggests that findings derived from a genetic murine melanoma model are relevant to human tumors and that low Siah2 levels could serve as a marker to stratify patients for ICT therapy." (PMID 31911617, 2020). "Inhibition of SIAH2 ubiquitin ligase blocks melanoma tumorigenesis." (PMID 30583572, 2018). "The ubiquitin ligase Siah2 has been described to be implicated in the regulation of both hypoxia response and Ras/MAPK signaling, thus ubiquitin ligase Siah represents a potential target for inhibition in melanoma." (PMID 26213971, 2015). "Thus, targeting SIAH2 could be beneficial to impair melanoma growth and development." (PMID 33800394, 2021). "To evaluate Siah2 function in the tumor environment, we injected cells of the BRAF-mutant melanoma line YUMMER1.7 into syngeneic wild-type (WT) or Siah2−/− mice." (PMID 31911617, 2020). "Low SIAH2 and FOXP3 expression is identified in immune responsive human melanoma tumors." (PMID 31911617, 2020). "MiR-335 binds to 3′-UTR of SIAH2 and decreases expression of SIAH2, which in turn increases the expression of HDAC3 to confer anti-cancer drug sensitivity in anti-cancer drug-sensitive melanoma cells, such as Malme3M cells." (PMID 30583572, 2018).
lung carcinoma (9 papers, 2011 to 2022). "The authors demonstrated that SIAH2 plays a critical pathogenic role in human lung cancer and, therefore, opened up a possibility of inhibiting SIAH action as a new anticancer target." (PMID 26580787, 2015). "Our findings indicate an important association between the expression of SIAH2 and lung cancer, which is also associated with the histological tumor grade, 18FDG uptake and with a decrease in the expression of SIAH2 substrates such as DYRK2." (PMID 26580787, 2015). "We observed a significant increase in DYRK2 expression in healthy lung specimens compared to corresponding lung cancer samples, suggesting that SIAH2 overexpression is associated with decreased expression of its substrates." (PMID 26580787, 2015). "In particular, mutual regulation has been described for SIAH2 and DYRK2; indeed, an increase in the SIAH2 protein has been observed in lung cancer tissue and linked to DYRK2 downregulation." (PMID 32751160, 2020). "The percentage of tumor cells that expressed SIAH2 increased with the histological tumor grade, being highest in poorly differentiated lung cancer specimens." (PMID 26580787, 2015). "We observed that SIAH2 expression was highly detectable in both major types of human lung cancer, being the expression predominantly nuclear." (PMID 26580787, 2015). "For this purpose, total proteins were extracted from the same 76 lung cancer specimens used above, and SIAH2 protein expression in lung cancer tissue compared to normal lung tissue was examined by Western blot." (PMID 26580787, 2015). "For the first time ever, we evaluated SIAH2 expression at different levels in primary lung cancer compared to adjacent normal lung tissue." (PMID 26580787, 2015). "Our results provide insight into the potential use of SIAH2 as a novel target for lung cancer treatment." (PMID 26580787, 2015). "SIAH2 protein expression in lung cancer samples was compared to that of the corresponding healthy tissue after normalization to actin signal intensities, and expressed as relative OD expression (Representative gel in S1 Fig)." (PMID 26580787, 2015). "For example, SIAH2 protein expression is significantly enhanced in human lung cancer and may serve as a novel target for lung cancer therapy." (PMID 35999505, 2022). "For instance, SIAH2 serves as an oncoprotein with elevated expression in lung cancer." (PMID 33842469, 2021). "Furthermore, higher expression of SIAH2 is observed in lung cancer and it plays oncogenic roles in castration-resistant prostate cancer." (PMID 33376136, 2021). "Specifically, our findings suggest that the analysis of SIAH2 could improve the diagnosis of lung cancer, and could deepen the current knowledge of its prognosis." (PMID 26580787, 2015). "The observed results herald the possible use of SIAH2 as a prognostic biomarker of lung cancer." (PMID 26580787, 2015). "To evaluate the biological significance of SIAH2 expression in human lung cancer, we examined the relationship between different clinicopathological characteristics and changes in SIAH2 expression levels (mRNA and protein) in tumors compared to healthy lung tissue." (PMID 26580787, 2015). "To further examine whether endogenous SIAH2 protein expression changes with lung tumor aggressiveness, we analyzed SIAH2 expression in different human lung cancers, including well-differentiated ADC, poorly differentiated ADC and SCC." (PMID 26580787, 2015).
lung carcinoma (continued). "More importantly, an increased correlation between SIAH2 expression and tumor grade was detected, suggesting that this protein could be used as a prognostic biomarker to predict lung cancer progression." (PMID 26580787, 2015). "In order to test whether SIAH2 expression could be correlated with lung carcinogenesis, we decided to evaluate SIAH2 expression and its localization pattern in lung cancer by immunohistochemistry in the complete patient cohort." (PMID 26580787, 2015). "We asked whether TYK2 evokes STAT3 signaling in lung cancer cells and if SIAH2 can attenuate this process." (PMID 24833526, 2014). "Furthermore, in addition to those genes previously associated with lung cancer, TSGs and oncogenes known to be deregulated in other cancer types–such as PRDM2 and SIAH2, respectively – were also altered at the genetic, epigenetic and gene expression levels." (PMID 22629454, 2012). "We next investigated whether SIAH2 protein expression is altered in human lung cancer." (PMID 26580787, 2015). "Recently, Muller and colleagues have demonstrated how SIAH2 accelerates the proteasomal degradation of TYK2, leading to STAT3 inactivation in lung cancer cells." (PMID 26580787, 2015). "We then analyzed the possible impact of the previously demonstrated mutual regulation between SIAH2 and DYRK2 in human lung cancer by immunohistochemistry." (PMID 26580787, 2015). "In summary, these data suggest that higher SIAH2 levels correspond to lower pSTAT3 and less MMP1 expression in human lung cancers." (PMID 24833526, 2014). "SIAH2 protein and mRNA levels were found to be higher in samples of patients with lung cancer and exhibited a negative correlation with DYRK2 expression." (PMID 33376136, 2021). "Because STAT1 belongs to a genetic signature predicting lung cancer patient survival, effects of SIAH2 on STAT1 and the immunological control of tumorigenesis are possible, i.e. SIAH2 may act as tumor promoter via blocking STAT1." (PMID 24833526, 2014). "Moreover, we show that SIAH2 reduces TYK2 and the TYK2-dependent activation of STAT3 in lung cancer cells." (PMID 24833526, 2014). "As we found that transfection of SIAH2 reduces the conversion of the metabolic substrate MTT by cells (data not shown), we conclude that high levels of SIAH2 may equally reduce the vitality of lung cancer cells." (PMID 24833526, 2014).
gastric cancer (6 papers, 2017 to 2025). A primary or metastatic malignant neoplasm involving the stomach. "In contrast, another study showed that the downregulation of filamin-C by acetylated Siah2 increased the invasiveness of gastric cancer cells." (PMID 34717622, 2021). "The aim of this study was to evaluate Siah2 phosphorylation status under the influence of H. pylori infection and its impact in gastric cancer progression." (PMID 33536006, 2021). "An association between ETS2 and TWIST1 was also confirmed in Helicobacter pylori-infected gastric cancer cells (GCCs), where the two genes were found to enhance SIAH2 expression." (PMID 29299035, 2017). "Further work is needed to clarify whether HDACi increase the acetylation of SIAH2, which has yet only been reported in gastric cancer cells, and if this posttranslational modification controls oncoprotein stability." (PMID 40877230, 2025). "Induced expression of ETS2, Twist1 and Siah2 was found in gastric cancer biopsies compared with noncancerous gastric tissue." (PMID 33825941, 2021). "In the gastric cancer cells AGS, Kato III and MKN45, H. pylori infection induced an expression of Siah2, in a E26 transformation-specific sequence 2 (ETS2)- and Twist-related protein 1 (Twist1)-dependent manner, which was accompanied by increased invasiveness and migration." (PMID 33825941, 2021). "The increased acetylation of Siah2, absence of PHD3 and accumulation of HIFα were detected in the H. pylori-infected human gastric metastatic cancer biopsies and in invasive murine gastric cancer tissues." (PMID 33825941, 2021).
breast tumor (5 papers, 2011 to 2022). "In particular, Src phosphorylates SIAH2 in vitro and leads to tyrosine phosphorylation and activation of SIAH2 in breast tumor cell lines." (PMID 32560326, 2020). "For example, SIAH2 expression correlates with breast tumor progression and malignancy and STAT1 exerts growth-inhibitory properties preventing mammary carcinogenesis in mice." (PMID 24833526, 2014). "Targeting SIAH2, the most apical regulator identified in the hypoxic response pathway, may be a suitable option for anticancer therapy in this breast tumor subtype." (PMID 21306611, 2011). "(F) Heatmap of the expression levels of SIAH2 and DBC1 in human normal breast tissues and breast tumor tissues." (PMID 35913115, 2022).